GFAP (glial fibrillary acidic protein)
Diseases named in the same sentence as GFAP in open-access papers (continued):
Sharing a sentence is not in itself a finding about the gene and the disease.
tumor (continued). "Cells accumulating H-1PV transcripts and NS1 were found mainly in areas staining positive for glial fibrillary acidic protein (GFAP) and epidermal growth factor receptor (EGFR) expression, suggesting virus replication in tumor cells." (PMID 28967558, 2017). "The mean fluorescence intensity of spinal GFAP and IBA-1 immunoreactivity were greatly increased in the tumor group compared with the sham group (p < 0.01)." (PMID 28587280, 2017). "Increased levels of astrocytic (GFAP) and neuronal (β-Tubulin III) markers in BIX01294-treated tumor spheres were confirmed at protein levels." (PMID 27934912, 2016). "In order to model the spectrum of MYCN-driven neoplasms in mice, we transgenically overexpressed MYCN under the control of the human GFAP-promoter that, among other targets, drives expression in neural progenitor cells." (PMID 27769070, 2016). "Both tumor types exhibited classic histology, and similar expression patterns for expected Shh-MB neural markers (Atoh1, TUBB3 and GFAP) and Hh target genes (Gli1, Mycn and Ccnd1)." (PMID 27823583, 2016). "Immunohistochemical (IHC) analysis showed diffuse expression of GFAP, OLIG2 and SOX2 consistent with a tumor of glial lineage." (PMID 26817999, 2016). "Tumour-derived cultures are usually similar to neural stem cell cultures in that NES-, GFAP-, OLIG2- and TUBB3-positive cells are all present." (PMID 27991551, 2016). "Glial fibrillary acidic protein (GFAP) in TJ905 cell and stem-like cell group showed the transplanted tumor originated from astrocytes." (PMID 26136642, 2015). "Immunohistochemical analysis of tumor tissue demonstrated upregulation of NG2, Ki67 (proliferation marker), PDGFRα, PDGFRβ and GFAP." (PMID 25987129, 2015). "Because tumor cell inoculation induced CXCL1 increase in spinal astrocytes, we then examined astrocytes activation by checking GFAP expression in the spinal cord." (PMID 24580964, 2014). "The small epithelioid areas of tumor had strong diffuse immunoreactivity for S100, CD56, and synaptophysin, with lesser GFAP immunostaining, estimated at 1/5 of the small epithelioid cells." (PMID 24321241, 2014). "In this sense, it has been demonstrated in vivo that not only neoplasic GFAP-positive astrocyte-like cells express CTGF, but that even GFAP-negative cells in the tumor can also express CTGF." (PMID 23383241, 2013). "This is demonstrated by the significant increase in IBA1 and GFAP labelled cells following both internal carotid artery and direct injection of CRCTU Walker 256 tumour cells when compared to the culture medium injected groups." (PMID 23374226, 2013). "The survival rates of the CMV promoter-transfected U251 and U87 tumor cells and MRC-5 cells were all lower compared with the GFAP promoter-transfected cells." (PMID 23420532, 2013). "As demonstrated by immunohistochemistry, glial fibrillary acidic protein (GFAP) and S100 Protein were consistently expressed by tumour cells." (PMID 23426283, 2013). "Immunohistochemistry (IHC) demonstrated the tumor cells were positive for smooth muscle actin (SMA), glial fibrillary acidic protein (GFAP), S-100, and vimentin." (PMID 23642050, 2013). "Immunohistochemistry is useful for confirming myoepithelial differentiation in MEC, such that all tumours are positive for at least one epithelial marker, cytokeratin or EMA, and most also express either S100 or GFAP." (PMID 22452794, 2012). "These cells then merge with the expanding tumor cells to populate it with GFAP, NFP and Syn +ve cells which acquire the haphazard pattern seen in the general tumor substance." (PMID 21080952, 2010). "The patterns of neuronal differentiation have been detailed in this work including the localisation of neural markers [GFAP, NFP and Syn] by tumor cells in relation to pigmentation." (PMID 21080952, 2010).
tumor (continued). "We have investigated the tumor forming potential of two GBM cell lines, U251 and U87, expressing different levels of GFAP and Nestin." (PMID 21304179, 2010). "Immunohistochemically, tumor cells are positive for both epithelial markers (EMA and CK) and myogenic markers (alpha-SMA and calponin), variably together with S-100 protein and GFAP." (PMID 20356364, 2010). "MGNTs are World Health Organization grade III and IV tumors that always present numerous glial fibrillary acidic protein (GFAP)- and a few neurofilament protein (NFP)-positive tumor cells." (PMID 20181261, 2010). "Tumor cells in the perimantle zone show high NFP [65%] and Syn [35.4%] positivity with very low GFAP [6.9%] correlating with the positivity in the outer layers." (PMID 21080952, 2010). "This suggests that most GFAP +ve cells proliferate into NFP and Syn +ve cells which then populate the tumor." (PMID 21080952, 2010). "The pattern of neural differentiation is assessed by immunopositivity for HMB45, GFAP, NFP and synaptophysin has been compared in: [a] the general tumor [b] tumor-vascular complexes and [c] perimantle zone [PC] on serial frozen and paraffin sections." (PMID 21080952, 2010). "Conversely, the tumor cells of both areas stained negatively for each of α-smooth muscle antigen (α-SMA), p63 and glial fibrillary acidic protein (GFAP), which were myoepithelial cell markers." (PMID 18559079, 2008). "After differentiation with 10% FBS for 7 days, immunocytochemistry was performed on U251ρ0 tumor spheroids using antibodies for neuron-specific β III-tubulin and, astrocyte-specific GFAP." (PMID 18985161, 2008). "GFAP, SOX9 and type IV collagen were strongly positive in some parts of the tumours cultured for 4 and 8 weeks, while only occasional c-kit-positive areas were observed in tumours cultured for 8 weeks." (PMID 10389991, 1999). "The developing tumour was analysed by light and electron microscopy and by immunocytochemical localization of transcription factors SOX9 and c-kit, glial fibrillary acidic protein (GFAP) and type IV collagen." (PMID 10389991, 1999). "Glial fibrillary acidic protein (GFA) was assayed in nerve-tumour extracts and located in these tumours by indirect immunofluorescence study." (PMID 339941, 1978). "To determine whether Prickle4 induction directly influences endothelial cells or instead functions in an indirect, tumor cell‐derived paracrine manner, we performed immunofluorescent staining for Prickle4, CD31, and GFAP." (PMID 41236163, 2026). "Immunhistochemically, tumor cells were positive for glial fibrillary acidic protein (GFAP), CD34 V600E-mutant BRAF, and CD34, negative for R132H-mutant IDH1." (PMID 41340779, 2026). "Circulating tumor cells (CTCs) (4′,6-diamidino-2-phenylindole (DAPI) + glial fibrillary acidic protein (GFAP) + epidermal growth factor receptor (EGFR) + CD45−CD66b−) zero-converted after therapy (16 CTCs in 7.5 ml blood detected on day −9 versus zero CTCs on day +190)." (PMID 40016450, 2025). "Most studies have demonstrated that tumor cells express S-100, CD68, and Vimentin, whereas markers such as CK, Syn, CgA, Desmin, and pituitary hormones are typical negative, with the majority of cases also showing negativity for GFAP." (PMID 40860841, 2025). "In contrast, the combination of GFAP and PTX exhibited enhanced anti-tumor activity." (PMID 39940603, 2025). "Furthermore, a significant difference in NLRP3 expression was observed in tumor cells exposed to the two PTX-containing scaffolds, the most suitable for PTX delivery being GFAP (p < 0.05)." (PMID 39940603, 2025). "After 12 h post-seeding, statistically increased levels of caspase-1 were observed in contact with GF + PTX compared with GF (p < 0.0001) and GFAP + PTX compared with GFAP (p < 0.0001), suggesting the anti-tumor and pro-inflammatory properties of PTX in contact with metabolically active tumor cells." (PMID 39940603, 2025).
tumor (continued). "Immunohistochemical staining revealed that the tumor was positive for reticular fiber staining, BRAFV600E, Syn, Olig-2, and CD34 and scattered positive for glial fibrillary acidic protein (GFAP) and neuron-specific nuclear protein (NeuN), and Ki-67 was low (approximately 2%–5%)." (PMID 39995830, 2025). "Histologic findings of Olig2 positivity with focal to absent GFAP warrant further evaluation for this tumor entity." (PMID 40724977, 2025). "The results revealed that WSCD2 protein expression was strongly related to gender (χ2 = 4.820, p = 0.028) and tumor grade (χ2 = 12.837, p = 0.002) but not linked to age, histological classification, IDH1-R132H mutation status, and GFAP expression." (PMID 38415455, 2025). "Immunofluorescence staining confirmed that p‐p38 predominantly colocalized with IBA‐1 and NFAT1 but not with NeuN or GFAP in the spinal dorsal horn on day 14 post‐tumor inoculation." (PMID 39957627, 2025). "In addition, glial fibrillary acidic protein (GFAP), typically expressed in NSCs, is found at higher levels in grade III MGs, suggesting a correlation between stem cell-like properties and tumour aggressiveness." (PMID 39316249, 2025). "Hyaline degeneration of blood vessel walls is rare or absent, pseudorosette tumour cells around blood vessels have slender cell processes and are negative for GFAP." (PMID 39963393, 2025). "Glial markers such as glial fibrillary acidic protein (GFAP) are only expressed in reactive astrocytes, but not in tumor cells." (PMID 40711574, 2025). "The presence of enteric glia using S100B and GFAP staining in CRC tumor tissue and an increase compared to normal human colon tissue was previously shown by other groups in a limited number of human samples." (PMID 40580485, 2025). "The immunophenotype of the tumor did not reveal a clear line of origin, with negative staining for GFAP, OLIG2, S100 protein, SOX10, desmin, pankeratin, synaptophysin, and only focally positive vimentin." (PMID 40159593, 2025). "In the groups both with and without relapse, C5b-9 was frequently detected on GFAP-positive (tumor-specific) circulating EVs with high VEGF-A expression, whereas C5b-9 was significantly less frequently detected on EVs with low VEGF-A expression (p < 0.05)." (PMID 39996852, 2025). "Our study did not highlight specific gene expression changes in GFAP+ tumor cells that significantly influenced TTR." (PMID 39423857, 2025). "Our studies have shown that in both groups, C5b-9 is detected quite frequently on GFAP-positive (tumor-specific) circulating EVs with high VEGF-A expression, whereas C5b-9 was significantly less frequently detected on GFAP-positive EVs with low VEGF-A expression." (PMID 39996852, 2025). "While GFAP was negative within the neoplasm, the areas of neoplasm infiltration overlapped with glial inflammation at the neoplasm margins." (PMID 40417366, 2025). "Moreover, GFAP + PTX promoted PTX activity and determined a considerable inhibition of the viability of tumor cells when compared with GF + PTX (p < 0.01)." (PMID 39940603, 2025). "Analysis of coronal sections across the tumor-bearing brain showed that a majority of IL-33-positive cells (≥80%) also co-express OLIG2, and more than half (around 60%) co-express CNPase while co-labeling with GFAP is seen in 5% of the IL-33-positive cells." (PMID 39931535, 2025). "Endothelial NRP1 positivity combined with limited vascular-astrocytic interaction and aberrant GFAP expression in SHH-MB may contribute to dysregulated angiogenesis and tumor progression." (PMID 40805120, 2025). "The tumor cells were immunohistochemically positive for GFAP, ATRX, and H3 K27me3, but negative for synaptophysin, IDH1 R132H, and H3 K27M." (PMID 39432011, 2025). "GFP cells in sh-DUSP8-GFP generated tumor showed a round shape morphology suggesting a reduced capacity to acquire a glial phenotype as confirmed by negative labeling for GFAP." (PMID 41029387, 2025).
tumor (continued). "In the groups both with and without relapse, C5b-9 was frequently detected on GFAP-positive (tumor-specific) circulating sEVs with high VEGF-A expression, whereas MAC was significantly less frequently detected on EVs with low VEGF-A expression (p < 0.05)." (PMID 39996852, 2025). "Immunohistochemistry revealed that the tumor cells were negative for glial fibrillary acidic protein (GFAP) and epithelial membrane antigen (EMA), whereas integrase interactor 1 (INI-1) expression was retained." (PMID 41216086, 2025). "Immunohistochemistry showed weak GFAP and vimentin expression, and the tumour was negative for cytokeratin (AE1/AE3), S100 and EMA." (PMID 41033792, 2025). "Cells in both tumor models retained proliferative and immature characteristics, as evidenced by c-MYC overexpression and increased MKI67 expression, and decreased expression of MAP2 and GFAP compared to their respective controls." (PMID 40917877, 2025). "The genes with a significant correlation between the level of expression and the spatial proximity between tumor and stromal spots that are enriched in leptomeningeal tissues (patterns observed in multiple samples) include MT3, SERPINA3, and glial fibrillary acidic protein (GFAP)." (PMID 38866016, 2024). "However, the spatial expression gradient we observed in GFAP and MT3 expression, with upregulation at the tumor-stroma interface in leptomeningeal metastases, suggests that neural damage occurs directly at the tumor/stroma interface." (PMID 38866016, 2024). "Using immunohistochemistry, tumor cells diffusely expressed GFAP and showed no or only focal expression of Olig2 and SOX10." (PMID 38581034, 2024). "The tumor cells were negative for GFAP, Olig-2, and only individual tumor cells expressed synaptophysin." (PMID 38926750, 2024). "Using immunohistochemistry, all tumors except one (case #14 which presented a GFAP staining in a part of the tumor) expressed GFAP diffusely, and presented no or only focal immunopositivity for Olig2 and SOX10." (PMID 38581034, 2024). "For example, cells with both GFAP and vimentin have been reported to be more aggressive than vimentin-negative/GFAP-positive tumor cells." (PMID 38295184, 2024). "Expression of Cx43 and the presence of GFAP-positive reactive astrocytes were observed in the peritumoral zone with infiltrating cancer cells, but were absent in the necrotic tumor core." (PMID 38489314, 2024). "Approximately 6% of cases were detected before the surgical excision but not after excision, and in 7.5% of cases, GFAP-positive CTCs were only detected after tumor excision, but not before it." (PMID 39057054, 2024). "Immunohistochemistry (IHC) shows the tumor stain positive for S100 glial fibrillary acidic protein (GFAP) and P16, whereas it was negative for CD117, DOG1, smooth muscle actin (SMA), and CD34." (PMID 39027743, 2024). "Immunostaining revealed that the tumor cells were negative for glial fibrillary acidic protein and oligodendrocyte transcription factor 2, but they were diffusely positive for CD56 and S100 protein." (PMID 38255255, 2024). "Immunohistochemically, tumor cells reveal positivity for GFAP only, while they are negative for MAP2, OLIG2, and CD34." (PMID 38544524, 2024). "The absence of GFAP expression indicates significantly undifferentiated tumor cells but does not suggest tumor progression." (PMID 38715021, 2024). "Human glioma cells may undergo an alteration in GFAP splicing, with a dominance of the GFAPδ isoform in GBM, affecting the aggressiveness of the tumor." (PMID 38671983, 2024). "Analysis of tumor‐bearing brains revealed that targeting TAGLN expression in GSCs reduced the expression levels of TAGLN, the proliferation marker Ki67, and the GSC marker SOX2, but increased levels of the GFAP differentiation marker and Cleaved Caspase3." (PMID 38087889, 2024).
tumor (continued). "Our results revealed regional heterogeneity in the tumor-like structures of GBs, with OLIG2+ stem cell populations occupying hyperoxic, highly nutritious regions at the periphery, while GFAP+ differentiated cells resided in chronic hypoxic necrotic regions at the core." (PMID 38390494, 2024). "We then examined the GFAP, NeuN, and IBA1 expression around the tumor border." (PMID 38884167, 2024). "In terms of immunohistochemical staining, the tumor cells were positive for S-100, vimentin and Ki-67 (1%) and negative for glial fibrillary acidic protein (GFAP) and epithelial membrane antigen (EMA)." (PMID 36761947, 2023). "Histological evaluation of qMCP-deficient and WT tumors showed reduction of tumor-associated macrophages by IBA1 staining with no changes in P2RY12, CD31, OLIG2, GFAP, and CD44 positive areas." (PMID 37012245, 2023). "The colocalization of GFAP- and IL-1β-positive signals was high in the tumor-bearing animals, while no detectable IL-1β was observed in the control mice." (PMID 37749707, 2023). "We found a significant decrease in GFAP and CSPGs expression in the tumor periphery region, which did not overlap with the GBM region (GFP-labeled U87 MG), of KDS2010-treated mice." (PMID 37468961, 2023). "By immunohistochemistry, the tumor cells expressed synaptophysin, chromogranin, NKX2.2 (diffuse, nuclear), GFAP (patchy), SMI31 (neurofilament) (focal, cytoplasmic), and TdT (diffuse, nuclear), while lacking expression of CD99, TTF-1, CK 20, MCPyV, PHOX2B, Olig2, OCT3/4, CD45, CD3 and PAX5." (PMID 38031161, 2023). "These include telomerase promoter-based assays or the use of a variety of tumor markers including oncofetal chondroitin sulfate, a GBM CTC antibody cocktail, glial fibrillary acidic protein (GFAP) and polyploidy detection by FISH with variable reported CTC isolation rates of 20.6–77%." (PMID 37568669, 2023). "Furthermore, glial fibrillary acidic protein (GFAP) – an intermediate filament expressed by astrocytic lineages, including a majority of huGBM – was only focally expressed in both tumor models." (PMID 38213329, 2023). "As we sought to understand why OBSCs could provide such an accommodating niche for patient tumor engraftment, we again measured OBSC astrocyte activation around tumor tissue via GFAP." (PMID 37192626, 2023). "Anti-GFAP and anti-S100 antibodies were used to stain sections of tumor tissue with and without PNI." (PMID 37799274, 2023). "Unexpectedly, immunostainings highlighted tumor components displaying a robust and diffuse GFAP immunoreactivity, usually not present in MB, along with tumor areas displaying a classical immunoreactivity for Synaptophysin." (PMID 36941703, 2023). "In contrast, positive OLIG2 and GFAP staining (> 5% of tumor cells) was present in many SHH-1A and SHH-1B, but absent in SHH-2." (PMID 35501487, 2022). "A large proportion of tumor cells were positive for GFAP and negative for synaptophysin, desmin, and CK." (PMID 36333774, 2022). "Secondly, GFAP-positive fibrillary astrocytes mingling with tumor cells without clasmatodendrosis suggested that GFAP autoimmunity does not equate to autoimmune GFAP astrocytopathy." (PMID 36552122, 2022). "The proteins include GFAP, YKL‐40 and IGFBP-2, which are either cytoskeletal proteins in astroglial tumors, or overexpressed genes of the tumor cells that may be involved in tumorigenesis." (PMID 35673564, 2022). "Therefore, both GFAP and MAP2 cells were found to be targeted by the IUE approach within the tumor parenchyma." (PMID 36538906, 2022). "Examination of lineage-specific marker expression revealed four principal clusters corresponding to tumor and glia (using the SOX2, OLIG2, GFAP markers), lymphoid cells (CD45, CD3, CD8, and CD4), myeloid cells (CD45, PU.1, CD163, CD68, and CD11b), and endothelial cells (CD31)." (PMID 35973991, 2022). "U87-MG-derived tumor cells stained positively for Ki67, but the majority of the tumor cells were negative for GFAP." (PMID 35402232, 2022).